CEBPD (CCAAT enhancer binding protein delta)
Diseases named in the same sentence as CEBPD in open-access papers (continued):
Sharing a sentence is not in itself a finding about the gene and the disease.
glioma (continued). "This study found that the knockdown of UBE2I, CEBPD, and DSG2, and the overexpression of PUM2 in vitro all inhibited the capacities for migration, invasion, and VM in glioma cells." (PMID 32997416, 2020). "UBE2I knockdown, CEBPD knockdown, and PUM2 overexpression significantly inhibited the capacities for migration, invasion, and VM in glioma cells." (PMID 32997416, 2020). "The purpose of this study is to clarify the SUMO2/3‐induced SUMOylation in glioma, as well as the expression and interaction of PUM2, CEBPD, and DSG2, and the role of these molecules in regulating VM of glioma." (PMID 32997416, 2020). "This study found that the expression of UBE2I was significantly increased in glioma cells, which promoted PUM2 SUMOylation, led to the degradation of PUM2 protein, and inhibited the role of PUM2 protein in the degradation of CEBPD mRNA." (PMID 32997416, 2020). "The results of this study confirmed that UBE2I, CEBPD, and PUM2 have the potential to be new molecular targets, and the research on the treatment of gliomas needs to be further explored." (PMID 32997416, 2020). "Our experimental results showed abnormal expression of UBE2I, PUM2, CEBPD, and DSG2 in glioma cells." (PMID 32997416, 2020). "Further analysis of the genomic database and tissue array revealed that the expression levels between CEBPD and PDGFA were coincident in glioma patient samples." (PMID 31300060, 2019). "We show that CEBPD is responsive to IL-1β stimulation and enhances the transcription and expression of PDGFA, which, in turn, promotes glioma stemness." (PMID 31300060, 2019). "A microarray expression analysis in mesenchymal gliomas found that expression of BHLHE40 and a number of other transcriptional regulators of mesenchymal transition including CEBPB, CEBPD, and STAT3 correlates with the extent of necrosis." (PMID 27096627, 2016). "First, the mRNA levels of CEBPD in glioma tissues was investigated by qPCR, including 5 normal brain samples, 14 astrocytomas (A, grade II), 15 anaplastic astrocytomas (AA, grade III), and 31 GBMs." (PMID 37059730, 2023). "Given that DN-ATF5 triggers apoptosis of glioma and other cancer cell types, identification of CEBPB, CEBPD and CCDC6 as direct DN-ATF5 targets suggested that these too may play required roles in tumor cell growth and survival." (PMID 36831248, 2023). "The experimental results found that the upregulation of UBE2I in glioma tissues and cells promotes the SUMOylation of PUM2, which decreases not only the stability of PUM2 protein but also decreases the inhibitory effect of PUM2 on CEBPD mRNA." (PMID 32997416, 2020). "In gliomas, DN‐ATF5 acts as a tumor suppressor by blocking the transcriptional activity of CEBPD." (PMID 32997416, 2020). "The upregulation of CEBPD promotes the binding to the upstream promoter region of DSG2 gene, further upregulates the expression of DSG2, and finally promotes the development of glioma VM." (PMID 32997416, 2020). "Moreover, consistent with interference with CEBPB, CEPBD and ATF5 activities, in T98G and other non-glioma cancer lines, Dpep and Bpep suppressed expression of direct CEBPB/CEBPD targets IL6 and IL8 and of direct ATF5 and CEBPB target asparagine synthetase (ASNS)." (PMID 36831248, 2023). "However, the role of SUMO2/3, PUM2, CEBPD, and DSG2 in glioma VM has not been reported." (PMID 32997416, 2020).
hepatocellular carcinoma (14 papers, 2010 to 2025). A malignant tumor that arises from hepatocytes. "Under pathological conditions, HEY1 and CEBPD exhibit opposing roles in hepatocellular carcinoma: HEY1 promotes metastasis, while CEBPD functions as a tumor suppressor gene." (PMID 41421763, 2025). "In previous cancer studies, CEBPD has been suggested to induce cell growth arrest and apoptosis in hepatocellular carcinoma and prostate cancer and thus function as a tumor suppressor." (PMID 31300060, 2019). "Low expression of CEBPD in a variety of cancers has been observed, including hepatocellular carcinoma and cervical cancer, and the hypermethylation in the CEBPD promoter mediated by polycomb group complex and DNA methyltransferase contributes to the silencing of CEBPD expression at this context." (PMID 31300060, 2019). "In addition, studies in human cervical and hepatocellular carcinoma cells have shown recruitment of DNA methyltransferases and silencing of the human C/EBPδ (CEBPD) promoter by hypermethylation." (PMID 20426839, 2010). "According to our previous study, CEBPD is downregulated in hepatocellular carcinoma (HCC) and cervical cancer, serving as a tumor suppressor." (PMID 36035213, 2022). "In hepatocellular carcinoma cells, however, CEBPD promoter activation and C/EBPδ levels decreased in the presence of enhanced β-catenin amounts following GSK3 inactivation." (PMID 32231133, 2020).
cervical carcinoma (13 papers, 2010 to 2025). A carcinoma arising from either the exocervical squamous epithelium or the endocervical glandular epithelium. "CEBPD has been linked to a variety of cancers, including colorectal, breast and cervical cancer, and is frequently downregulated." (PMID 37047552, 2023). "The current investigation elucidated that CEBPD serves as an upstream regulatory factor for key genes, including MYC, IL6, JUN, RRM2, and VEGFA, all of which have been linked to an unfavorable prognosis in cervical cancer patients." (PMID 38926832, 2024). "For instance, CEBPD can upregulate proapoptotic genes, including PPARG2 and GADD153, in cervical cancer and caspase-8 and caspase-3 in prostate cancer." (PMID 28099155, 2017). "Recent years have borne witness to a burgeoning interest in comprehending the multifaceted roles that CEBPD plays across various cancer types, including but not limited to cervical cancer and pancreatic ductal adenocarcinoma." (PMID 38926832, 2024). "These genes, particularly CEBPD, SLPI, KRT16, and NOTCH1, may serve as potential biomarkers at the mRNA level for the course of cervical cancer development, and warrant further study as it relates to understanding HPV-dependent carcinogenesis." (PMID 34944802, 2021).
Alzheimer disease (12 papers, 2007 to 2024). A progressive, neurodegenerative disease characterized by loss of function and death of nerve cells in several areas of the brain leading to loss of cognitive function such as memory and language. "Up-regulation of CEBPD, encoding a transcription factor of cytokines and other pro-inflammatory response genes, elevated in the brain of Alzheimer's disease patients and itself induced by inflammatory stimuli, ties in with this assumption." (PMID 17244347, 2007). "The activation of CEBPD has been observed in many autoimmune and age-associated chronic inflammation diseases, such as atherosclerosis, type 2 diabetes, rheumatoid arthritis (RA), Alzheimer’s disease (AD) and Parkinson’s disease." (PMID 25591788, 2015). "CEBPD has been previously implicated in peripheral immune challenge and CEBPD is up-regulated after traumatic brain injury in rats and in brains from patients with Alzheimer's disease." (PMID 18673548, 2008). "Together, our findings demonstrate a critical function for the astrocytic CEBPD, and point to miR-135a antagonist as an attractive therapeutic target for the treatment of Alzheimer’s disease." (PMID 26208701, 2016). "CEBPD may play a role in neurological disease and Alzheimer’s disease, possibly because of CEBPD-mediated regulation of inflammatory processes." (PMID 36834565, 2023). "Furthermore, an increase in apoptotic astrocytes was observed in AppTg/Cebpd−/− mice [an Alzheimer disease mouse model (APPswe/PS1/E9 bigenic) crossed with Cebpd-deficient mice], thereby suggesting that CEBPD plays a functional role in contributing to the anti-apoptotic ability of astrocytes." (PMID 25591788, 2015). "There are also studies on the relationship between genes and cognitive function that show that five genes, PFKFB4, PDK3, KIAA0319L, CEBPD, and PHC2T, have the potential to recognize Alzheimer’s disease." (PMID 39328989, 2024).
acute myeloid leukemia (9 papers, 2008 to 2023). Acute myeloid leukemia (AML) is a group of neoplasms arising from precursor cells committed to the myeloid cell-line differentiation. "In this study, we show that in acute myeloid leukemia (AML) cells, high expression of vitamin D receptor gene (VDR) is needed for strong and sustained upregulation of CEBPB gene, while the moderate expression of VDR is sufficient for upregulation of CEBPD in response to 1,25D." (PMID 29966306, 2018).
leukemia (8 papers, 2010 to 2024). A malignant (clonal) hematologic disorder, involving hematopoietic stem cells and characterized by the presence of primitive or atypical myeloid or lymphoid cells in the bone marrow and the blood. "Initially, studies suggested CEBPD acts as a tumor suppressor in leukemia, prostate cancer and hepatocellular carcinoma." (PMID 26307680, 2015). "In liver cancer and leukemia, CEBPD plays a tumor suppressive role by inducing cell death." (PMID 33436575, 2021). "A total of 100 TFs with silenced promoters were downregulated relative to AML, including hematopoietic regulators and genes known to be involved in leukemia, such as CEBPA, CEBPD, KLF4, IRF4 or MEIS1." (PMID 38972954, 2024). "In the present study, transcription factor CCAAT/enhancer binding protein delta (CEBPD) was responsive to the anticancer drug bortezomib, a clinical and highly selective drug for leukemia treatment, and contributed to bortezomib-induced cell death." (PMID 29120412, 2017).
breast tumors (7 papers, 2010 to 2023). "Moreover, “loss of function” alterations of CEBPδ and promoter methylation of the C/EBPD locus have been observed in primary human breast tumors." (PMID 21072181, 2010).
Obesity (7 papers, 2021 to 2025). Accumulation of substantial excess body fat. "These hub genes were associated with progression of obesity associated type 2 diabetes mellitus and first five (CEBPD, TP73, ESR2, TAB1 and MAP 3K5) of them might be linked with targeted therapy." (PMID 33902539, 2021). "Investigation has demonstrated that CEBPD (CCAAT enhancer binding protein delta) is involved in obesity." (PMID 33902539, 2021). "The hub genes CEBPD, TP73, ESR2, TAB1, MAP 3K5, FN1, UBD, RUNX1, PIK3R2 and TNF, which might play an essential role in obesity associated type 2 diabetes mellitus was further screened." (PMID 33902539, 2021).
pancreatic cancer (6 papers, 2019 to 2024). "To assess whether C/EBPδ may act as a tumor suppressor in pancreatic cancer, we first analyzed CEBPD mRNA expression levels in pancreatic ductal adenocarcinomas and in adjacent control tissue in publicly available gene expression datasets (GSE62452 and GSE16515)." (PMID 32906832, 2020). "As both PANC-1 and Mia PaCa-2 cells already express very low or undetectable C/EBPδ levels, we turned to Capan-2 cells that, according to public gene expression datasets, show the highest CEBPD levels of all routinely used pancreatic cancer cell lines." (PMID 32906832, 2020). "Interestingly, the analysis identified enrichment of multiple TFs including TCF4, WT1, CEBPD, CEBPB, SUZ12, and ZFP281 across all stages of pancreatic cancer progression." (PMID 30644396, 2019).
rheumatoid arthritis (6 papers, 2012 to 2025). A chronic, systemic autoimmune disorder characterized by inflammation in the synovial membranes and articular surfaces. "The up-regulation of CCAAT/enhancer binding protein delta (CEBPD) has frequently been observed in macrophages in age-associated disorders, including rheumatoid arthritis (RA)." (PMID 23028973, 2012). "Recent studies have shown that macrophage CEBPD participates in the progression of various diseases including osteoporosis, rheumatoid arthritis (RA), atherosclerosis, lung injury, and cancers." (PMID 40990024, 2025). "CCAAT/enhancer binding protein delta (CEBPD) is a member of the CCAAT/enhancer binding protein (C/EBP) family and has been shown to be activated in many inflammatory diseases, including AD and rheumatoid arthritis." (PMID 24788683, 2015).
Sepsis (6 papers, 2016 to 2025). Sepsis is defined as life-threatening organ dysfunction caused by a dysregulated host response to infection. "Our sequencing analysis indicated a significant increase in CEBPD in patients with sepsis and a decline in therapy, suggesting that imatinib can suppress inflammation and apoptosis through direct downregulation of CEBPD." (PMID 40524944, 2025). "CEBPD and PDK4 were significantly upregulated in the sepsis group (L group), but downregulated in the imatinib group (M group), consistent with our sequencing results." (PMID 40524944, 2025). "Further pathway analysis substantiated that the transcription factors CEBPD and RUNX1, known to be activated temporarily during steady-state and sepsis-induced myelopoiesis, were featured in CD14 Mono_Activated." (PMID 37821442, 2023). "Additionally, we found that the expression of CCAAT/enhancer-binding protein delta (CEBPD) and pyruvate dehydrogenase kinase 4 (PDK4) increased in the sepsis group but decreased in the imatinib group." (PMID 40524944, 2025).
urothelial carcinoma (6 papers, 2015 to 2024). A malignant neoplasm derived from the transitional epithelium of the urinary tract (urinary bladder, ureter, urethra, or renal pelvis). "• MYC and CEBPD coamplification predicts poor outcomes in urothelial carcinoma." (PMID 34954904, 2021). "CEBPD/miR-193b-3p axis had key roles in cisplatin response of urothelial carcinoma cells in which CEBPD up regulates the miR-193b-3p and improved cisplatin cytotoxicity in urothelial carcinoma." (PMID 33183321, 2020). "The aim of this study is to decipher the underlying mechanisms of CCAAT/enhancer‐binding protein delta (CEBPD)‐enhanced glycolysis as well as the biological significance of CEBPD and MYC coamplification in urothelial carcinoma (UC)." (PMID 34954904, 2021).
atherosclerosis (5 papers, 2017 to 2025). A disease characterized by the build-up of fatty material and calcium deposition in the arterial wall resulting in partial or complete occlusion of the arterial lumen. "have reported that CEBPD is mainly expressed in macrophages of atherosclerotic plaques and that CEBPD deficiency in bone marrow cells suppresses atherosclerotic lesions in ApoE-/- mice, indicating that macrophage CEBPD plays a functional role in the pathogenesis of atherosclerosis." (PMID 40990024, 2025). "CEBPD and RUNX1 were identified as the key regulators for both atherosclerosis-associated cell states despite the higher expression of Cebpd in Vcam1+ SMCs and Runx1 in Col2a1+ SMCs." (PMID 37060905, 2023). "This is consistent with previous reports showing CEBPD to be up-regulated in many inflammatory settings including atherosclerosis." (PMID 28585919, 2017). "Similarly, the mRNA level of CEBPD in the peripheral blood cells of patients with atherosclerosis is inversely correlated with carotid intima-media thickness, a biomarker of subclinical atherosclerosis and a predictor of future cardiovascular events." (PMID 40087290, 2025).
liver cancer (5 papers, 2012 to 2021). An epithelial or non-epithelial malignant neoplasm that arises from the liver. "We further found that the resistance of EGFR-overexpressed liver cancer cells to sorafenib is associated with low activity of AMP-activated protein kinase (AMPK) and CCAAT/enhancer binding protein delta (CEBPD) as well as insufficient autophagic activation." (PMID 33681180, 2021). "Here, we found that CEBPD expression was also induced by metformin in liver cancer cells." (PMID 28099155, 2017). "Strong CEBPD activation could strengthen the death of liver cancer cells." (PMID 28099155, 2017).
lung carcinoma (5 papers, 2017 to 2025). "Previous research has demonstrated that CEBPD promotes lymphangiogenesis and metastasis in lung cancer by regulating the HIF-1α/VEGF-C signaling pathway." (PMID 40895068, 2025). "On the other hand, recent studies have demonstrated that CEBPD plays an oncogenic role when endogenous CEBPD expression is relatively higher or during inducible CEBPD expression in some cancer types, such as bladder cancer and lung cancer." (PMID 31300060, 2019). "It was discovered that CCAAT-enhancer binding protein-delta (C/EBP-δ) upregulates VEGF-C and VEGFR-3 expression in LECs in lung cancer, where hypoxia could induce this transcription factor's expression." (PMID 33263009, 2020).
ovarian carcinoma (5 papers, 2020 to 2025). A malignant neoplasm originating from the surface ovarian epithelium. "CEBPD is a vital transcriptional regulator in ovarian cancer." (PMID 32997416, 2020).
pancreatic ductal adenocarcinoma (5 papers, 2020 to 2025). An infiltrating adenocarcinoma that arises from the epithelial cells of the pancreas. "Data mining of publicly available microarray datasets showed that CEBPD gene expression is significantly decreased in pancreatic ductal adenocarcinomas versus healthy pancreatic tissue." (PMID 32906832, 2020). "Indeed, CEBPD expression levels correlate with stromal gene signatures in five out of six publicly available datasets containing pancreatic ductal adenocarcinoma (PDAC) samples as determined using ESTIMATE." (PMID 32906832, 2020).
bladder urothelial cancer (4 papers, 2019 to 2025). "In bladder urothelial carcinoma, gefitinib treatment significantly decreases the expression of CEBPD and enhances the sensitivity of bladder urothelial cancer cells to cisplatin and paclitaxel." (PMID 32997416, 2020). "In a bladder urothelial carcinoma model, CEBPD expression is upregulated by STAT3 activation and promotes cancer drug resistance." (PMID 31300060, 2019).
COVID-19 (4 papers, 2022 to 2024). A disease caused by infection with severe acute respiratory syndrome coronavirus 2. "In contrast, severe COVID-19 cases exhibited activation of CEBPD in peripheral immune cells, while CEBPB was exclusively activated in respiratory epithelial cells." (PMID 37936693, 2023). "In the other datasets, CEBPB increased in the patients with Kawasaki and CoV2-MyoC, and CEBPD increased in the patients with COVID-19 and Kawasaki." (PMID 36225942, 2022). "Similarly, for CD14 and CD16 monocyte cells in severe COVID-19, CEBPD and FOS were particularly activated in the two cell types, and CEBPD upregulated S100A8 and S100A9." (PMID 37936693, 2023). "Similarly, SPDEF and ELF3 were found to be activated in squamous cells, and CEBPD and FOS were shared between CD14 and CD14 monocytes in severe COVID-19." (PMID 37936693, 2023).
diabetes (4 papers, 2008 to 2025). "Western blotting further confirmed that the protein levels of S100A4, ARPC1B, and CEBPD were significantly upregulated.These results collectively suggest that S100A4, ARPC1B, and CEBPD may serve as core biomarkers in the common mechanisms underlying diabetes and kidney stones." (PMID 40718484, 2025). "The mechanisms of S100A4, ARPC1B, and CEBPD in kidney stones and diabetes should be further explored in wet lab experiments." (PMID 40718484, 2025). "Among 101 machine learning models, S100A4, ARPC1B, and CEBPD were identified as the most significant interacting genes linking diabetes and kidney stones." (PMID 40718484, 2025). "Overall, our study suggests that S100A4, ARPC1B, and CEBPD may serve as valuable biomarkers that play a crucial role in the shared pathogenesis of kidney stones and diabetes." (PMID 40718484, 2025). "We identified three biomarkers—S100A4, ARPC1B, and CEBPD—that may play critical roles in the shared pathogenesis of diabetes and kidney stones." (PMID 40718484, 2025). "One of the strengths of this study is the identification of three novel biomarkers for diabetes and kidney stones using machine learning methods: S100A4, ARPC1B, and CEBPD." (PMID 40718484, 2025).